APP (amyloid beta precursor protein)
Diseases named in the same sentence as APP in open-access papers (continued):
Sharing a sentence is not in itself a finding about the gene and the disease.
Senile plaques (continued). "Aβ is a ~ 4.5 kDa peptide derived from the processing of amyloid precursor protein (APP), and is the primary component of senile plaques in the brains of patients with AD." (PMID 41219801, 2025). "Increased expression of DMT1 has been observed in senile plaques of AD patients, as well as in APP/SS1 transgenic mice and cellular lines that overexpress APP." (PMID 39020435, 2024). "SIRT1 levels are brain region-dependent in AD, being able to degrade the Aβ peptide in primary astrocytes and to reduce ROS and peroxidation levels in APP/PS1 AD model, decreasing senile plaques and improving learning and memory activities." (PMID 36755296, 2023). "βA derives from the amyloid precursor protein (APP) and forms intracerebral senile plaques (SP) that are morphologically heterogeneous and graded according to the Thal scheme." (PMID 36830944, 2023). "Melatonin improved cognitive function in APP/PS1 transgenic mice and decreased ROS and senile plaques." (PMID 35983247, 2022). "SIRT1 overexpression, furthermore, reduces AD pathology and decreases the formation of β-amyloid protein and senile plaques in APPSWE/ind (J20) and APPswe/PS1M146L (APP/PS1) mice." (PMID 35269588, 2022). "It has been described that processing amyloid precursor protein (APP) through the amyloidogenic pathway produces amyloid-β peptide (Aβ), which accumulates in the brain to produce senile plaques." (PMID 34681567, 2021). "In the cerebral zone of APP/PS1 mice, one most common animal AD model, the content of Aβ and number of senile plaques are elevated, while the learning capability and memory function of these mice are impaired." (PMID 34708522, 2021). "APP/PS1 is a commonly used mouse model of AD, with obvious senile plaques and microglia activation at the age of 4 months." (PMID 34632701, 2021). "Additional studies revealed that P2X7R positive microglial cells surrounding senile plaques express the catalytic NADPH subunit (gp91phox) and produce ROS species in APP/PS1 mice." (PMID 32581707, 2020). "It is thought that hypercholesterolemia can enhance the activities of γ-secretase and β-secretase, facilitate the metabolism of amyloid precursor protein (APP), aggravate Aβ deposition, promote the formation of senile plaques and then lead to AD." (PMID 29556189, 2018). "As a popular rodent model of AD, APP/PS1 mice develop amyloid plaques and behavioral deficits around 6–7 months, presenting an age-dependent manner of Aβ deposition in senile plaques." (PMID 30107760, 2018). "BJJS-treated APP/PS1 mice appeared to have reductions of Aβ deposition and senile plaques, and showed higher levels of neurotrophic factors in the brain." (PMID 29190943, 2017). "APP/PS1 double transgenic mice generate a large number of Aβ and develop a lot of senile plaques both in the hippocampus and cortex during the animal growth period." (PMID 29190943, 2017). "The APP/PS1 model mice exhibited a marked increase in the number and size of Aβ-immunoreactive senile plaques in the cortex and hippocampus." (PMID 25780429, 2015). "It was hypothesized that AD’s neuropathology was largely due to the overexpression of amyloid precursor protein (APP) as APP produces amyloid ß protein, the main component of senile plaques, and is located on chromosome 21." (PMID 39194513, 2024). "AD, which is typified by neurofibrillary tangles (NFTs) and the aggregation of senile plaques that are formed by the amalgamation of amyloid-β protein, a truncated product of APP (Amyloid precursor protein) cleaved by the enzyme β-secretase (BACE1), is the foremost contributor to NDDs." (PMID 39412683, 2024). "The most significant differences between 10-month-old APP/PS1 mice on a HFD compared to APP/PS1 on STD were found in the polar glycolipids-gangliosides (GM2 36:1 and GM3 36:1), which were previously found to be colocalized with senile plaques and astrocytosis." (PMID 37686722, 2023).
Senile plaques (continued). "In addition, ECH significantly reduced the deposition of senile plaques in the brain and decreased the expression of BACE1 in APP/PS1 mice through activating PI3K/AKT/Nrf2/PPARγ pathway." (PMID 35665898, 2022). "In 1984 Dr. Glenner and Dr. Wong isolated and identified APP, but it was not until 1991 and 1996 that mutations in the APP, PSEN1, and PSEN2 genes were identified as having a causative role in the production of Aβ peptides and senile plaques." (PMID 33806317, 2021). "Here, we show that, at 4∼5 months old (an age at which there are no obvious senile plaques), APP/PS1 mice exhibit abnormal mitochondrial fission and morphology together with gliosis." (PMID 34955809, 2021). "Hippocampal senile plaques number was marginally decreased in HFD-fed APP/PS1 mice but was not significant (P > 0.05)." (PMID 33291072, 2020). "Amyloid-β (Aβ) peptides cleaved from amyloid precursor protein (APP) are the key molecules involved in AD pathogenesis; deposition of Aβ in the brain as senile plaques and cerebral amyloid angiopathy (CAA) likely triggers a cascade of events leading to disease onset." (PMID 24904407, 2014). "Interestingly, these mice exhibited increased levels of APP and Aβ without the formation of senile plaques, suggesting a potential role for α7nAChRs within the tripartite interplay involving α7nAChRs, Aβ, and tau." (PMID 39000011, 2024). "The reduction in senile plaques may have resulted from the promotion of non-amyloidogenic APP processing through activation of ADAM10 by SIRT1." (PMID 35052635, 2022). "Due to the deposition of mutant amyloid precursor protein (APP) and progeria protein‐1 proteins in the cortex and the hippocampus, Aβ is deposited inside the cell, leading to the formation of plaques, and outside the cell, leading to the formation of senile plaques." (PMID 37786418, 2022).
cerebral amyloid angiopathy (115 papers, 2006 to 2025). "This study found cerebral amyloid angiopathy in two cases with the APP mutation (specifically V717 and V717L)." (PMID 40149496, 2025). "For example, cerebral amyloid angiopathy is caused by the β-amyloid precursor protein (APP), whose gene is predicted to interact with 428 candidate variants in this realistic setting." (PMID 35486646, 2022). "Amyloid Protein Precursor (APP) gene duplication is associated with Cerebral Amyloid Angiopathy which leads to intracerebral hemorrhagic stroke." (PMID 36016137, 2022). "Beyond AD, most genetic forms of cerebral amyloid angiopathy (CAA) are also due to mutations in the APP gene." (PMID 35052700, 2021). "In our previous study, WSB.APP/PS1 showed the highest levels of cerebral amyloid angiopathy (CAA), associated with vascular leakage and neuronal loss." (PMID 33567283, 2021). "Previously, though amyloid plaques linked the histopathology of early and late-onset AD, all mutations in APP resulted in early-onset AD or cerebral amyloid angiopathy." (PMID 32022689, 2020). "Some mutations in the gene for amyloid precursor protein (APP) cause severe cerebral amyloid angiopathy (CAA), with resultant strokes and brain hemorrhages." (PMID 26175713, 2015). "Of the APP mutations causing AD or cerebral amyloid angiopathy, four occur at the E693 position of the protein, the Dutch (E693Q), Arctic (E693G) and Italian (E693K) mutations and a deletion (E693Δ)." (PMID 25312309, 2014). "Duplicated APP regions containing several genes or APP only have been clinically linked to early-onset AD often with extensive cerebral amyloid angiopathy." (PMID 24377094, 2013). "Furthermore, these protective effects led to prevention of Aβ accumulation, cerebral amyloid angiopathy, and even synapse loss in APP/PS1 mice." (PMID 36959217, 2023). "Familial AD patients with spastic paraparesis are likely to have a PSEN1 mutation while familial AD patients with cerebral hemorrhage caused by cerebral amyloid angiopathy may have APP mutations." (PMID 24955352, 2014). "The cerebral amyloid angiopathy is likely caused by the failure of Aβ elimination from the brain parenchyme, while a role of vascular smooth muscle and endothelial cells by abnormal processing of endothelial amyloid precursor protein (APP) has also been suggested." (PMID 28617802, 2017). "Carriers of the Dutch mutation (APP E693Q) are characterized clinically by focal symptoms related to recurrent cerebrovascular events, usually followed by dementia, in their 40s and 50s, and pathologically by cerebral amyloid angiopathy with rare amyloid plaque pathology." (PMID 24955352, 2014). "A single intravenous injection of Aβ seeds derived from human AD brain extracts into amyloid precursor protein/presenilin 1(APP/PS1) mice resulted in cerebral amyloid angiopathy within 180 days after injection." (PMID 40077014, 2025). "We find that APP-SAA KI mice show cerebral amyloid angiopathy (CAA)-like Aβ aggregation in meningeal and cerebral blood vessels at the age of 8.5 months." (PMID 40830489, 2025). "RNAi therapeutic silencing of APP has recently moved to clinical trials for AD and cerebral amyloid angiopathy." (PMID 41022326, 2025). "Even though the resulting mice did not exhibit cerebral amyloid angiopathy pathology with age, crossing them with APP knock-in mice yielded mice with increased cerebral amyloid angiopathy pathology." (PMID 38816814, 2024). "APP is mainly associated with neurodegenerative disease, including cerebroarterial amyloidosis (cerebral amyloid angiopathy, APP-related and Alzheimer’s disease, familial 1)." (PMID 37240249, 2023). "Cerebral amyloid angiopathy is characterized by the depositions of amyloid-β peptide (Aβ), which is a cleavage product of the amyloid precursor protein (APP), in leptomeningeal arteries and cortical capillaries in the brain." (PMID 35886033, 2022).
cerebral amyloid angiopathy (continued). "This vascular deposition of Aβ resembles cerebral amyloid angiopathy (CAA) observed in different APP transgenic mouse models, and very commonly in human AD brains." (PMID 34663480, 2021). "Inhibiting NOX with the naturally occurring compound, apocynin, or genetic deletion of gp91phox in mice (Tg2576) overexpressing mutant amyloid precursor protein (APP), attenuates cerebral amyloid angiopathy (CAA)." (PMID 32823544, 2020). "Familial AD mutations in APP and PSEN1 genes have been utilized to develop mouse models bearing Aβ pathologies including amyloid plaques and cerebral amyloid angiopathy." (PMID 30894120, 2019). "The development of cerebral amyloid angiopathy (CAA) in WSB.APP/PS1 coupled with fibrin leakage suggests compromised vascular integrity and/or deficits in amyloid clearance." (PMID 31150388, 2019). "Our previous study also showed that knocking out the Aqp4 gene exacerbates brain Aβ deposition and cerebral amyloid angiopathy in APP/PS1 mice." (PMID 30867902, 2019). "APP V717I presents with amyloid plaques, neurofibrillary tangles, cerebral amyloid angiopathy, and, in some cases, with amygdala Lewy bodies." (PMID 30045758, 2018). "Previous pathological studies reported a particularly severe cerebral amyloid angiopathy (CAA) with post codon 200 PSEN1 mutations and amyloid beta coding domain APP mutations." (PMID 30090657, 2018). "Mutations in APP that result in amino acid substitutions of Glu22 cause FAD (Arctic (E22G), Italian (E22K), and Osaka (ΔE22)) and cerebral amyloid angiopathy (Dutch (E22Q))." (PMID 28970487, 2017). "APP mutations are associated with AD1, early-onset progressive autosomal recessive dementia, early-onset AD with cerebral amyloid angiopathy, and hereditary amyloidosis with cerebral hemorrhage Dutch type, Italian type, or Iowa type." (PMID 22482072, 2012). "The main component of the amyloid plaques and cerebral amyloid angiopathy is the amyloid-β (Aβ) peptide, derived from a larger amyloid precursor protein (APP), by the proteolytic actions of β-secretase and γ-secretase." (PMID 22412990, 2012). "Notably, deletion of CD36 reduces cerebral amyloid angiopathy in amyloid precursor protein (APP)-overexpressing mice, likely by enhancing brain-to-blood clearance via endothelial CD36 rather than microglial mechanisms." (PMID 41301546, 2025). "While APP/PS1 mice develop Aβ plaques and neurofibrillary tangles, they may not exhibit other pathological features seen in human AD, such as cerebral amyloid angiopathy, widespread neuroinflammation, or significant neuronal loss." (PMID 38675490, 2024). "Moreover, Alnylam Pharmaceuticals has developed ALN-APP, which fuses a synthetic siRNA targeting APP to a proprietary 2’-O-hexadecyl (C16) lipophilic conjugate, for AD and Cerebral Amyloid Angiopathy." (PMID 39075597, 2024). "In addition, cerebral amyloid angiopathy and related microhemorrhage was more frequent in female APP/PS1 mice." (PMID 38324617, 2024). "This is in contrast to previous studies in APP TG mice, where CMBs were located in the neocortex and, to a lesser degree in the thalamus, likely because of the different mechanisms of progression in cerebral amyloid angiopathy related CMBs." (PMID 32641073, 2020). "In addition, APP is known to play a role in cerebral amyloid angiopathy and is believed to be involved in processes related to neural cell adhesion, neuronal synaptic plasticity, synaptogenesis, and neurite growth." (PMID 32327964, 2020). "For example, APP/PS1 transgenic mice overexpressing human apoA-I were characterized by an increase in plasma HDL-C levels, and a parallel improvement of memory deficit and attenuation of Aβ-associated neuroinflammation and cerebral amyloid angiopathy." (PMID 33287338, 2020). "Our findings support the concept that pathological expression and processing of APP in senescent cerebrovascular endothelium may play an important role in pathogenesis of cerebral amyloid angiopathy and AD." (PMID 29348391, 2018).
cerebral amyloid angiopathy (continued). "The present study was undertaken to disclose whether oxidative stress may contribute to the cerebral amyloid angiopathy by affecting endothelial APP processing." (PMID 28617802, 2017). "Here, we reported that the deletion of AQP4 exacerbated cognitive deficits of 12-moth old APP/PS1 mice, with increases in Aβ accumulation, cerebral amyloid angiopathy and loss of synaptic protein and brain-derived neurotrophic factor in the hippocampus and cortex." (PMID 26526066, 2015). "One key discovery, the isolation and sequencing of the gene encoding the larger amyloid precursor protein (APP), was made possible by the biochemical analysis of β-amyloid containing blood vessels (CAA, cerebral amyloid angiopathy) and amyloid plaques consisting of Aβ." (PMID 24252153, 2013). "These investigations may help to establish the APP 23 model as a suitable tool for further studies on the pathogenesis of cerebral amyloid angiopathy." (PMID 23174128, 2012). "Additionally, we analysed the APP-L705V (Piedmont) mutation, which is associated with pure cerebral amyloid angiopathy (CAA) that presents without parenchymal Aβ plaques or tau pathology but with recurrent intracerebral haemorrhage." (PMID 40281586, 2025). "However, because the extra copy of APP leads to increased beta-amyloid peptide (Aβ) accumulation in DS, we hypothesized that there would be more extensive and widespread cerebral amyloid angiopathy (CAA) with age in DS relative to sporadic AD." (PMID 29195510, 2017). "After infusing ThioS in APP/PS1 mice, we observed strong in vivo labeling of amyloid plaques and cerebral amyloid angiopathy (CAA) in the brain." (PMID 39896645, 2025). "The APP/PS1/APOA-I triple-transgenic mouse model exhibits higher levels of serum HDL and improved cerebral amyloid angiopathy and neuroinflammation compared with the APP/PS1 double-transgenic model." (PMID 40573187, 2025). "Overexpression of human ApoA1 in circulation was shown to prevent learning and memory impairments in APP/PS1 transgenic mice, partly by suppressing neuroinflammation and cerebral amyloid angiopathy." (PMID 35782939, 2022). "Previous studies have shown that overexpression of human ApoA1 in the circulation can prevent learning and memory impairment in APP/PS1 transgenic mice, partly by reducing neuroinflammation and cerebral amyloid angiopathy." (PMID 39484667, 2022). "Deleting AQP4 from APP/PS1 mice resulted in increased accumulation of amyloid both as plaques in parenchyma and as cerebral amyloid angiopathy (CAA) around blood vessels, as well as increased soluble Aβ levels." (PMID 32398151, 2020). "The authors showed that the absence of ABCB1 results in a significant disturbance of Aβ removal in a transgenic murine model of AD (APP/PS1+/−−ABCB1), leading to an increased intraparenchymal cerebral amyloid angiopathy." (PMID 29317984, 2017). "We observed a similar effect when cerebral amyloid angiopathy (CAA) was quantified, and a reduction of CAA was observed in APP/PS1-STZ mice (*p = 0.022 vs. APP/PS1-Sham)." (PMID 26156287, 2016). "While total β-amyloid (Aβ) load is unchanged across groups, Congophilic amyloid deposition was decreased in the parenchyma and significantly increased in the vasculature as cerebral amyloid angiopathy (CAA; vascular amyloid deposition) in HHcy APP/PS1 mice." (PMID 24991237, 2014). "Similarly, for the APP/PS1 mice in which the APP and PS1 mutant gene are drove by Prnp promoter, the female mice showed more Aβ plaque and phosphorylated tau protein burdens, more severe cerebral amyloid angiopathy, neuroinflammation, and gliosis." (PMID 32093751, 2020). "Furthermore, the APP+PS1 rats also showed vascular changes, including cerebral amyloid angiopathy with extensive Aβ deposits in cortical and leptomeningeal blood vessel walls and venous collagenosis." (PMID 29641600, 2018). "In APP/PS1/SphK1 tg mice, cerebral amyloid angiopathy also was reduced." (PMID 29662056, 2018).
cerebral amyloid angiopathy (continued). "Interestingly, Aβ was deposited as cerebral amyloid angiopathy (CAA) in large and small blood vessels within the brains of male and female APP/PSEN1 mice as well as Sorcs1 -/- x APP/PSEN1 mice." (PMID 26916443, 2016). "However, we cannot exclude that cerebral amyloid angiopathy (CAA), which is accrued in A/T mice compared to APP mice, contributed to the altered reactivity through other mechanisms." (PMID 23874687, 2013). "Apparent plaques and cerebral amyloid angiopathy (CAA) could be clearly observed from the APP/PS1 mice while no such features were found in WT mice, suggesting that obatoclax can bind to Aβs in vivo." (PMID 35919434, 2022). "In contrast, transgenic mice (APP/PS1) lacking ApoA1 showed increased amyloid deposition and astrogliosis in the cerebral cortex, as well as the development of cerebral amyloid angiopathy." (PMID 41516203, 2025).